FGFR2 (fibroblast growth factor receptor 2)
Diseases named in the same sentence as FGFR2 in open-access papers (continued):
Sharing a sentence is not in itself a finding about the gene and the disease.
paraganglioma (2 papers, 2019 to 2021). A benign or malignant neoplasm arising from paraganglia located along the sympathetic or parasympathetic nerves. "Tumors with dominant FGFR2 amplification included STAD (4.09%), OV (1.88%), pheochromocytoma and paraganglioma (PCPG) (1.12%), ESCA (0.55%), and PAAD (0.54%)." (PMID 33968743, 2021).
Peters anomaly (2 papers, 2012 to 2024). Peters anomaly (PA) is a congenital corneal opacity disorder characterized by a central corneal leukoma that obstructs the pupil leading to visual loss as well as absence of the posterior corneal stroma and Descemet membrane. "Although FGFR2 has been implicated in Peters anomaly, the molecular mechanisms remain unclear." (PMID 39484567, 2024).
renal fibrosis (2 papers, 2024). A final common manifestation of a wide variety of chronic kidney diseases characterized by glomerulosclerosis and tubulointerstitial fibrosis. "The increased expression levels of renal fibrosis-related genes (Grem2, Id3, Fst, Dcn) and renal damage-related genes (Runx1, Vtn, Clo6a2, Tnxb, Itga8, Timp2, Fgfr2, Fgf9) further supported the idea that miPEP31 deficiency exacerbated Ang II-induced kidney inflammation." (PMID 38992718, 2024). "As the transcription of Fgf10 and Fgfr2 depends on AR signaling, exposure to DBP disrupted the Fgf10/Fgfr2 signaling pathway in the kidneys, this being a crucial factor in the development of renal fibrosis." (PMID 39728417, 2024).
renal hypoplasia (2 papers, 2022 to 2024). Renal hypoplasia is a developmental anomaly in which one or both kidneys (unilateral or bilateral renal hypoplasia, respectively) have a deficit in the number of nephrons and may be small. "The impairment of FGFR1 and FGFR2 expression suggests the involvement of the observed markers in generating the CAKUT phenotype resulting in renal hypoplasia." (PMID 35216141, 2022).
reproductive system cancer (2 papers, 2019 to 2023). "Previously, we reported that the expression levels of FGFRs between carcinoma and para-carcinoma cells in patients with digestive or reproductive system cancers are significantly different, and FGFR2 and FGFR4 are closely related to the susceptibility of digestive and reproductive system cancers." (PMID 31523191, 2019).
salivary gland tumor (2 papers, 2008 to 2025). "The genetic heterogeneity in this cohort and in the literature suggests that a subset of sialoblastomas, particularly the “non-solid” variants lacking FGFR2 mutations, may represent congenital presentations of other salivary gland tumor types." (PMID 40906279, 2025).
schwannoma (2 papers, 2023 to 2024). A benign, usually encapsulated slow growing tumor composed of Schwann cells. "Also, FGFR2 had significantly increased in expression (estimate = 0.76) in the Schwannoma nuclei relative to non-tumor tissue in the adjusted model but was significantly decreased in expression (estimate = −0.52) in the unadjusted model." (PMID 36865335, 2023).
serous ovarian carcinoma (2 papers, 2016 to 2024). "The FGFR2::FAM76A case report is especially relevant since it occurred in a moderately differentiated serous ovarian carcinoma with the same FGFR2 mRNA breakpoint as the present case." (PMID 39759134, 2024). "FGF4, which binds FGFR2-IIIc with high affinity, was previously reported to be highly expressed in advanced-stage and poor-prognosis cases of serous ovarian cancer." (PMID 27677589, 2016).
signet-ring carcinoma (2 papers, 2018 to 2022). "With respect to major histological types, although sample numbers are low in these observations, the proportion of FGFR2-positive patients was numerically higher than that of HER2-positive patients for signet-ring carcinoma." (PMID 35585358, 2022).
uterine cancer (2 papers, 2021 to 2023). Primary or metastatic malignant neoplasm involving the uterine corpus and/or the cervix. "FGFR2 gene amplification mutations are prevalent in uterine cancers, and particularly in the endometroid histological type." (PMID 37465112, 2023). "In comparison, for UCEC, the role is less clear, although the tumorigenic effect of FGFR2 in uterine cancer is evident at high levels of FBXW4 (6D), in line with previous studies reporting mutations that provide constitutive activation of FGFR2 in a subset of endometrial cancer." (PMID 34408236, 2021).
acute kidney injury (1 paper, 2021). Sudden and sustained deterioration of the kidney function characterized by decreased glomerular filtration rate, increased serum creatinine or oliguria. "FGFR2 was found to be important in protection against the apoptosis of tubular cells in acute kidney injury, partly by stimulating the activation of extracellular signal-regulated kinase 1/2 (Erk1/2; also called mitogen-activated protein kinase 3/1)." (PMID 34360633, 2021).
adenomyosis (1 paper, 2025). The growth of endometrial tissue inside the muscular wall of the uterine corpus. "The mutation frequencies per subject, regardless of sampling depths, were as follows: in adenomyosis, KRAS: 33.3%, PIK3CA: 14.3%, and ARID1A: 14.3%, and in uterine endometrium, KRAS: 66.7%, PIK3CA: 57.1%, ARHGAP35: 52.4%, PPP2R1A: 33.3%, PIK3R1: 28.6%, and FGFR2: 19.0%." (PMID 40679511, 2025).
adenosarcoma (1 paper, 2017). A low grade malignant neoplasm characterized by the presence of a benign epithelial component (tubular and cleft-like glands) and a low grade sarcomatous component that contains varying amounts of fibrous and smooth muscle tissues. "Several cancer genes rarely mutated in adenosarcomas, such as DICER1 (11%), FGFR2 (11%), and BRCA2 (5%), were not mutated in any of the PTs analyzed." (PMID 28267263, 2017).
adrenal hyperplasia (1 paper, 2025). "Importantly, we also show that FGFR2 loss can fully prevent the development of Wnt/βCat–driven adrenal hyperplasia and that FGFR inhibitors can decrease aldosterone secretion." (PMID 40956622, 2025). "Together, these results demonstrate the capacity of Fgfr2 deletion in zG cells to fully prevent the development of βCat–driven adrenal hyperplasia and to block aldosterone excess following activation of RAAS." (PMID 40956622, 2025). "Additionally, we showed that inhibition of FGFR signaling was also able to lower aldosterone levels in our mouse model of βCat–driven adrenal hyperplasia (βCat-GOF) following genetic (Fgfr2 deletion) and pharmacological approaches." (PMID 40956622, 2025).
airway hyperresponsiveness (1 paper, 2016). "Interestingly, using a candidate-gene approach in a group of 2,108 children and adolescents, a haplotype of SNPs in intron 17 of the FGFR2 gene was found to be associated with atopy but not with airway hyperresponsiveness." (PMID 26999364, 2016).
alopecia (1 paper, 2022). Hair loss usually from the scalp. "Particularly, AChE and fibroblast growth factor receptor 2 (FGF-2) among the findings overlapped with the target protein derived when alopecia was explored as a disease keyword in the GeneCards database." (PMID 35181715, 2022).
anaplastic thyroid cancer (1 paper, 2015). "Sensitivity to FGFR inhibitors have been observed in patients harboring FGFR2 fusions with the same breakpoint as that found in the THJ-29T ATC cell line and thus testing for these fusions might provide a tractable therapeutic option for a subset of patients diagnosed with anaplastic thyroid cancer." (PMID 26680454, 2015).
ankylosis (1 paper, 2025). Fixation and immobility of a joint. "In a previous study, we defined the FGFR2 coding locus as an ankylosis susceptibility locus in (MRL/rpl × C3H/lpr) F1 mice, which develop spontaneous ankylosing arthropathy, as well as DBA/1J mice." (PMID 39919800, 2025).
anorectal malformation (1 paper, 2024). "According to these results, it is suggested that the AR and the Fgf10/Fgfr2 signaling pathways could be involved in the development of anorectal malformations in male rats exposed to DBP in utero." (PMID 39728417, 2024).
asthma (1 paper, 2016). "At the FGFR2 gene expression level, associations were identified with CD4+/CD8+ T-cell responses in severe asthma, dendritic cell response to Chlamydia pneumonia lung infection and PGE EP3 induced asthma (GEOprofile datasets GSE2276, GSE31773, GSE470, GSE12806)." (PMID 26999364, 2016).
atopic dermatitis (1 paper, 2024). "This is relevant in vivo, because bioinformatics analysis of bulk and single-cell RNA-seq data showed strongly reduced expression of FGFR2 in lesional skin of atopic dermatitis patients, which likely aggravates the inflammatory phenotype." (PMID 39340759, 2024).
bone metastasis (1 paper, 2017). Transfer of a neoplasm from its primary site to bones. "In present study, FGFR2 amplification was found to be associated with several clinicopathologic parameters, including younger age, poor ECOG performance status, extra-abdominal lymph node metastasis, bone metastasis, poorly differentiated histology, and Bormann type IV disease." (PMID 27802183, 2017).
cerebellar ataxia (1 paper, 2014). A neurological syndrome characterized by clumsy and uncoordinated movement of the limbs, trunk, and cranial muscles. "Altogether, our findings thus reveal the specific pro-differentiation, anti-apoptotic and cell positioning functions of FGFR2-mediated signaling in RG/BG precursors/cells during cerebellar development in the mouse, and might provide new mechanistic insights to the pathogenesis of cerebellar ataxias." (PMID 24983448, 2014).
cervical dysplasia (1 paper, 2020). "FGFR2 expression has been reported to be associated with cell growth and progression of cervical dysplasia." (PMID 33193890, 2020).
channelopathy (1 paper, 2017). Channelopathies are a group of diseases caused by the dysfunction of ion channel subunits or their interacting proteins. "This introduces LUAD as a potential TRPA1-modulated channelopathy, with TRPA1 and FGFR2 acting as valuable cancer biomarkers." (PMID 29038531, 2017).
chondrodysplasia (1 paper, 2025). "Taken as a whole, our results highlighted the various roles of FGFR2 and FGFR3 during endochondral bone repair and the positive action of FGFR3 antagonists in the context of fracture in FGFR3-related chondrodysplasia." (PMID 39837840, 2025).
chronic obstructive pulmonary disease (1 paper, 2022). A chronic and progressive lung disorder characterized by the loss of elasticity of the bronchial tree and the air sacs, destruction of the air sacs wall, thickening of the bronchial wall, and mucous accumulation in the bronchial tree. "FGFR2 and FGFR4 belong to the fibroblast growth factor receptor family which has been shown to mediate pro-inflammatory signaling in the liver and airway epithelium in chronic obstructive pulmonary disease." (PMID 35012443, 2022).
Craniofacial dysostosis (1 paper, 2014). A characteristic appearance resulting from defective ossification of craniofacial bones. "Activation of osteoblastic bone anabolism in the calvarial sutures is considered to be the essential pathologic condition underlying mutant FGFR2-related craniofacial dysostosis." (PMID 24489893, 2014).
cyst (1 paper, 2023). A sac-like closed membranous structure that may be empty or contain fluid or amorphous material. "Furthermore, we found that the interaction of FGFR2/FGF9 in tubular cells and cyst cells may play an important role in the induction of cyst cell formation." (PMID 37583898, 2023). "We focused on exploring the relationships between cyst cells and the other cell types, and we found that CDPC, PT, and the rest of the DCTs express Fgf9, which can bind to the Fgfr2 receptor in cyst cells; FGF9/FGFR2 interactions have been reported to induce cell proliferation." (PMID 37583898, 2023). "In addition to FGFR2/FGF9, we also found that SPP1/CD44 interactions between immune cells, especially macrophages, and cyst cells may play an important role in the induction of cyst cell formation." (PMID 37583898, 2023).
dengue (1 paper, 2024). "We observed that EPHB3, ERBB2, FGFR2, IGF1R, and RET are upstream regulators both of kinases shown to be important in previous dengue research and of kinases predicted by KiR." (PMID 38585651, 2024).
dental caries (1 paper, 2025). The decay of a tooth, in which it becomes softened, discolored, and/or porous. "In the previous report, the c.722dup FGFR2 variant was identified in a young boy with recurrent fractures beginning from infancy, low BMD, joint pain, dental caries, and headaches." (PMID 40362441, 2025).
dermatitis (1 paper, 2020). An inflammatory process affecting the skin. "We determined the levels of RTKs (VEGFR1, PDGFRB and FGFR2) from dermatitis patients and normal controls using meta-analyses." (PMID 32161331, 2020). "We found PDGFRB and FGFR2 were increased from dermatitis patients compared to normal control." (PMID 32161331, 2020).
dermatofibrosarcoma protuberans (1 paper, 2026). Dermatofibrosarcoma protuberans (DFSP) is a rare infiltrating soft tissue sarcoma, generally of low grade malignancy, arising from the dermis of the skin and characteristically associated with a specific chromosomal translocation t(17;22). "In dermatofibrosarcoma protuberans (DFSP), FGF19 activates downstream signaling pathways by binding to FGFR1 and FGFR2, thereby promoting cell proliferation, survival, and migration, and ultimately driving tumor growth." (PMID 41328353, 2026).
diffuse astrocytoma (1 paper, 2023). A low-grade (WHO grade II) astrocytic neoplasm. "These include diffuse astrocytoma, MYB- or MYBL1-altered; diffuse low-grade glioma, MAPK pathway-altered; polymorphous low-grade neuroepithelial tumor of the young (BRAF mutations and FGFR2 fusions); and infant-type hemispheric glioma (alterations in NTRK, ROS1, ALK, or MET)." (PMID 37509316, 2023).
ductal carcinomas (1 paper, 2024). "FGFR2 has been reported in the progression of ER-negative luminal ductal carcinomas, which are more aggressive and less responsive to treatment, suggesting that FGFR2 may have an effect promoting IDC progression to an ER-independent basal-like phenotype." (PMID 39596875, 2024).
endometrial adenocarcinoma (1 paper, 2009). "An endometrial adenocarcinoma with co-occurring FGFR2 and PTEN mutations was also identified." (PMID 19924296, 2009).
endometrioid tumor (1 paper, 2012). A benign, borderline, or malignant epithelial tumor of the female reproductive system characterized by the presence of glands and/or cysts lined by neoplastic cells that resemble endometrial cells. "Our data suggest that FGFR2 mutations occur more often in the well and moderately differentiated endometrioid tumors (G1, G2) compared to undifferentiated tumors and possibly identify the “bad actors” in an otherwise better prognosis histological subgroup." (PMID 22383975, 2012).
endothelial dysfunction (1 paper, 2020). In vascular diseases, endothelial dysfunction is a systemic pathological state of the endothelium (the inner lining of blood vessels) and can be broadly defined as an imbalance between vasodilating and vasoconstricting substances produced by (or acting on) the endothelium. "Enhanced levels of NK cell infiltrates were also associated with parameters indicative of endothelial dysfunction such as lowered angiogenesis scores and FGFR2 transcript levels." (PMID 32256495, 2020).
epithelial dysplasia (1 paper, 2015). "Therefore, expression of FGF-2 and FGFR-2 may serve as an adjunct to histopathologic assessment of epithelial dysplasia for evaluating progression and malignant transformation in PMOLs." (PMID 26465941, 2015).
epithelioid sarcoma (1 paper, 2021). An aggressive malignant neoplasm of uncertain differentiation, characterized by the presence of epithelioid cells forming nodular patterns. "We show that differential regulation of EGFR and FGFR2, and partial reversion of EMT in epithelioid sarcoma is induced by HDAC inhibitor panobinostat." (PMID 34281526, 2021).
estrogen resistance (1 paper, 2013). "Therefore, anti-estrogen resistance is associated with alternative splicing of FGFR2 and corresponding change in protein levels." (PMID 23758675, 2013).
follicular adenoma (1 paper, 2013). "In contrast, in follicular adenoma, we observed a significant reduction in FGFR-2-IIIb staining intensity, with no evident signal both in cell membrane and cytoplasm (C’, arrows in panel C’)." (PMID 23977259, 2013).
Follicular Cyst (1 paper, 2023). Cyst due to the occlusion of the duct of a follicle or small gland. "FGF7 regulated the PPAR signaling pathway (FABP5 and SCD) and the MAPK signaling pathway (FGF1, FGFR2, IL1A, TGFB1, and CSF1) and pathways in cancer (IL7, CD44, SMAD2, and MMP2) may be involved in the formation of follicular cysts." (PMID 38274662, 2023).
gallbladder tumors (1 paper, 2025). "Fibroblast growth factor receptor 2 (FGFR2) and IDH1 mutations are almost exclusive to intrahepatic tumors, whereas HER2 alterations are more common in gallbladder tumors and eCCA." (PMID 40940908, 2025).
ganglioglioma (1 paper, 2018). A well differentiated, slow growing neuroepithelial neoplasm composed of neoplastic, mature ganglion cells and neoplastic glial cells. "In the two gangliogliomas that progressed after initial resection of unknown extent, sequencing analysis that was performed on the recurrent tumors demonstrated FGFR2-INA fusion in one and BRAF p.V600E mutation in the other." (PMID 29880043, 2018).
gastric ulcer (1 paper, 2013). An ulcerated lesion in the mucosal surface of the stomach. "We found that diminished mRNA expressions of proangiogenic growth factors (PDGFB) and their receptors (VEGFR2, FGFR1, and FGFR2) in gastric ulcer margins were well correlated with the degree of thrombocytopenia in the cirrhotic patients." (PMID 23620752, 2013). "However, mRNA expressions of FGFR1 and FGFR2 were significantly decreased in the gastric ulcer margins of the cirrhotic patients compared to those of the non-cirrhotic patients, and that the mRNA expression of FGFR was well correlated with the platelet count in cirrhotic patients." (PMID 23620752, 2013). "We found that cirrhotic patients had diminished mRNA expressions of proangiogenic growth factors (PDGFB) and their receptors (VEGFR2, FGFR1, and FGFR2) in gastric ulcer margins compared with those of the non-cirrhotic patients." (PMID 23620752, 2013). "The cirrhotic patients had diminished mRNA expressions of PDGFB, VEGFR2, FGFR1, and FGFR2 in gastric ulcer margin when compared with those of the non-cirrhotic patients (p<0.05)." (PMID 23620752, 2013).
giant cell tumor (1 paper, 2017). A benign, intermediate, or malignant tumor that arises from the bone or soft tissue. "This sensitivity was consistent with the target expression patterns of giant cell tumor PDCs (FGFR2-IIIC mRNA expression in giant cell tumor PDCs originated from the right pulmonary nodule was increased significantly as compared to those originated from left)." (PMID 28445128, 2017). "A sensitive response was more significantly achieved for AZD4547 (FGFR2 inhibitor) in giant cell tumor PDCs originated from the right pulmonary nodule under the micropillar/microwell chip platform using 3D culture." (PMID 28445128, 2017).